MIR193A (microRNA 193a)
Synonyms: hsa-mir-193; hsa-mir-193a; MIRN193; MIRN193A; mir-193a
Gene: MicroRNA gene on chromosome 17 (31,559,996 to 31,560,083, forward strand). Ensembl gene ENSG00000207614.
Gene Ontology:
Biological process: miRNA-mediated post-transcriptional gene silencing
Homologues: Orthologues: chimpanzee ptr-mir-193a (100% identical), macaque mml-mir-193a (92% identical), pig ssc-mir-193a (86% identical), rabbit MIR193A (77% identical), guinea pig MIR193A (73% identical), zebrafish mir193a-2 (70% identical), mouse Mir193a (68% identical), zebrafish mir193a-1 (65% identical), Drosophila melanogaster mir-193 (48% identical). Paralogues in human: MIR193B (57% identical).
Diseases named in the same sentence as MIR193A in open-access papers:
MIR193A is named in the same sentence as 17 diseases in open-access papers, as found by Europe PMC text mining. Sharing a sentence is not in itself a finding about the gene and the disease. The quoted sentences say what the papers report.
lung carcinoma (2 papers, 2015 to 2019). "Downregulation of microRNAs in cancer can occur via a number of different mechanisms, and in the case of miR-193a-3p the promoter of the MIR193A gene is associated with CpG islands and is silenced by methylation in lung cancer and AML." (PMID 26125439, 2015). "The MIR193A gene lies within a CpG island, and previous studies in lung cancer, oral squamous cell carcinoma and AML have demonstrated a methylation-induced silencing of the MIR193A gene and corresponding downregulation of miR-193a-3p in tumor cells." (PMID 26125439, 2015). "In contrast, the hypermethylation of the MIR193A gene promoter region found in lung cancer, AML and ovarian cancer does not appear to contribute to miR-193a-3p downregulation in MPM, as we have suggested previously." (PMID 31289611, 2019).
ovarian carcinoma (2 papers, 2019). A malignant neoplasm originating from the surface ovarian epithelium. "In ovarian cancer, MIR193A is silenced by methylated modification and down regulation of MIR193A expression promotes tumor aggressiveness by losing function of targeting GRB7 and MAPK/ERK pathways." (PMID 31523496, 2019).
acute myeloid leukemia (1 paper, 2019). Acute myeloid leukemia (AML) is a group of neoplasms arising from precursor cells committed to the myeloid cell-line differentiation. "Despite the association of the MIR193A gene promoter with CpG islands and its confirmed silencing by methylation in NSCLC and acute myeloid leukemia (AML), methylation was excluded as a predominant cause of its downregulation in MPM cell lines and the causes for its reduction in MPM remain unknown." (PMID 31289611, 2019).
adrenocortical adenomas (1 paper, 2019). "Lower expression of MIR193A was observed in human aldosterone-producing adrenocortical adenomas, and was functioned as a tumor suppressor by targeting and restraining CYP11B2 expression both at mRNA and protein level." (PMID 31523496, 2019).
colorectal adenocarcinoma (1 paper, 2019). The most common type of colorectal carcinoma. "Another study confirms the tumor suppressor roles of MIR193A by perturbing KRAS function in colorectal adenocarcinoma, including reducing cell proliferation, increasing apoptosis, and inhibiting epithelial-mesenchymal transition." (PMID 31523496, 2019).
colorectal cancer (1 paper, 2019). A primary or metastatic malignant neoplasm that affects the colon or rectum. "The role of MIR193a in colorectal cancer and inflammatory bowel disease has also been broadly explored." (PMID 31523496, 2019).
gastric cancer (1 paper, 2019). A primary or metastatic malignant neoplasm involving the stomach. "Another group demonstrated that MIR193A played an important role in the regulation of gastric cancer." (PMID 31523496, 2019).
gastric tumors (1 paper, 2019). "Both gastric cell lines and human gastric tumors contained decreased levels of MIR193A." (PMID 31523496, 2019).
metastatic prostate carcinoma (1 paper, 2019). A carcinoma that arises from the prostate gland and has spread to other anatomic sites. "Similar results were gained by another research that MIR193A is downregulated in metastatic prostate cancer and is involved in HOTAIR/EZH2/miR-193a feedback loop to exert a tumor suppressive function in prostate cancer." (PMID 31523496, 2019).
prostate carcinoma (1 paper, 2019). A carcinoma that arises from epithelial cells of the prostate gland. "MIR193A is noticed to be upregulated in prostate cancer tissues and cell lines, with significant suppression of cell apoptosis induced by oxidative stress by targeting Bach2." (PMID 31523496, 2019).
tumor (4 papers, 2015 to 2023). "In addition, an in vitro study showed that upregulating MIR193A decreased tumor cell proliferation and migration, at least partly, by directly targeting cyclin D1 (CCND1) and ETS proto-oncogene 1 (ETS1) expression." (PMID 31523496, 2019). "MIR193A, located on 17q11.2, has been widely found to be dysregulated in tumor progression." (PMID 31523496, 2019).
MIR193A also shares sentences with these, for which no sentence is quoted: cancer (1 paper); inflammatory bowel disease (1); intellectual disabilities (1); oral squamous cell carcinoma (1); ovarian tumors (1); secondary tumors (1).